GSG1L (GSG1 like)
Description:
As a component of the inner core of AMPAR complex, modifies AMPA receptor (AMPAR) gating.
Synonyms: MGC18079; PRO19651; KTSR5831
Tractability: Antibody: UniProt places it where antibodies can reach, with medium confidence; UniProt predicts a signal peptide or a membrane-spanning region; its Gene Ontology location is reachable by antibodies, with medium confidence.
Gene: Protein-coding gene on chromosome 16 (27,787,526 to 28,063,754, reverse strand). Ensembl gene ENSG00000169181.
Subcellular location: Cell membrane; Synapse
Gene Ontology:
Molecular function: protein binding
Biological process: regulation of cell communication; regulation of postsynaptic neurotransmitter receptor internalization; regulation of signaling; regulation of transport
Cellular component: plasma membrane; postsynaptic density membrane; asymmetric synapse; glutamatergic synapse; Schaffer collateral - CA1 synapse; synapse
Genetic constraint (gnomAD): Loss-of-function variants: 24 observed, 29.81 expected, observed/expected ratio (o/e) 0.81, 90% interval 0.58 to 1.13. The synonymous counts are far from expectation, so gnomAD's model fits this gene poorly and the ratio says little. Missense variants: 442 observed, 371.4 expected, observed/expected ratio (o/e) 1.19, 90% interval 1.1 to 1.29. Synonymous variants: 214 observed, 161.36 expected, observed/expected ratio (o/e) 1.33, 90% interval 1.19 to 1.49.
Homologues: Orthologues: chimpanzee GSG1L (100% identical), pig GSG1L (97% identical), macaque GSG1L (91% identical), mouse Gsg1l (89% identical), rat Gsg1l (89% identical), guinea pig GSG1L (84% identical), dog GSG1L (82% identical), rabbit GSG1L (75% identical), zebrafish gsg1l (66% identical), tropical clawed frog gsg1l (60% identical). Paralogues in human: GSG1 (40% identical), GSG1L2 (37% identical), TMEM202 (13% identical), LIM2 (11% identical), PMP22 (11% identical), NKG7 (11% identical), EMP1 (10% identical), EMP2 (10% identical), EMP3 (9% identical), CLDND2 (9% identical).
Diseases named in the same sentence as GSG1L in open-access papers:
GSG1L is named in the same sentence as 11 diseases in open-access papers, as found by Europe PMC text mining. Sharing a sentence is not in itself a finding about the gene and the disease. The quoted sentences say what the papers report.
adenoma (1 paper, 2020). A neoplasm arising from the epithelium. "Lesion-specific mutations in JMJD6, CNTNAP5 (adenoma-enriched), and GSG1L (carcinoma-enriched) were also identified." (PMID 32023847, 2020).
Anxiety (1 paper, 2024). Intense feelings of nervousness, tension, or panic often arise in response to interpersonal stresses. "No studies directly focusing on GSG1L gene sheep were detected in the literature, while a significant correlation between the expression level of GSG1L and composite anxiety level was reported in mice." (PMID 39227733, 2024).
colorectal cancer (1 paper, 2017). A primary or metastatic malignant neoplasm that affects the colon or rectum. "In a mouse genome-wide association study, GSG1L regulates glutamate receptor activity and was among the genes associated with a chromosome 15 colorectal cancer genetic susceptibility locus." (PMID 28257124, 2017).
glioma (1 paper, 2019). A benign or malignant brain and spinal cord tumor that arises from glial cells (astrocytes, oligodendrocytes, ependymal cells). "Additionally, analysis based on 1,018 Chinese glioma patients suggested that CELF5 (P < 0.001), GSG1L (P = 0.002), AMACR (P < 0.001), CYP27A1 (P < 0.001), CYP46A1 (P < 0.001), and CH25H (P = 0.046) were all prognostic indicators in Kaplan-Meier survival analysis." (PMID 32117422, 2019).
hepatoblastoma (1 paper, 2016). Hepatoblastoma (HB) is a malignant hepatic tumor and is the most common pediatric liver cancer. "The mRNA expression levels of CYP2B6, SPON1, and GSG1L in human hepatoblastoma (HepG2) cells were measured after 24 h of exposure to CAR agonists." (PMID 27010727, 2016).
Huntington disease (1 paper, 2015). Huntington disease (HD) is a rare neurodegenerative disorder of the central nervous system characterized by unwanted choreatic movements, behavioral and psychiatric disturbances and dementia. "Moreover, abnormal Gsg1l expression levels have been linked to Huntington's disease." (PMID 26483626, 2015).
osteoporosis (1 paper, 2017). A condition of reduced bone mass, with decreased cortical thickness and a decrease in the number and size of the trabeculae of cancellous bone (but normal chemical composition), resulting in increased fracture incidence. "We infer that the GSG1L gene is a loci for osteoporosis susceptibility with a view to developing our understanding of bone biology." (PMID 28383518, 2017).
cancer (3 papers, 2019 to 2020). A tumor composed of atypical neoplastic, often pleomorphic cells that invade other tissues. "However, there are no any reports or laboratory data on the relationship between cancer and the following genes: GSG1L, CRB1, XKR8, ZNF680, ZNF284, and ZNF780B, which is part of the 17-gene signature." (PMID 32596394, 2020). "GSG1L was inactive in the AMPA-type glutamate receptors (AMPARs) in cancer." (PMID 32117422, 2019). "The other six genes (GSG1 like (GSG1L), crumbs cell polarity complex component 1 (CRB1), XK-related 8 (XKR8), zinc finger protein 680 (ZNF680), zinc finger protein 284 (ZNF284), and zinc finger protein 780B (ZNF780B)) are not mentioned in the cancer research area until now." (PMID 32596394, 2020).
tumor (1 paper, 2025). "Our findings suggest that resistance-associated DEGs such as RAMP1, GSG1L, and GRIK4 may contribute to shaping the tumor microenvironment through interactions with M0/M2 macrophages and resting CD4+ memory T cells." (PMID 41234433, 2025).
GSG1L also shares sentences with these, for which no sentence is quoted: entropion (1 paper); epilepsy (1).